MMP3 (matrix metallopeptidase 3)
Diseases named in the same sentence as MMP3 in open-access papers (continued):
Sharing a sentence is not in itself a finding about the gene and the disease.
ischemic stroke (continued). "pGSN is cleaved in vitro by MMP-3, MMP-2, MMP-1, MMP-14 and MMP-9 which may be the cause of the severe depletion of pGSN observed in patients who suffer ischemic stroke." (PMID 22047744, 2011). "Additionally, while one meta-analysis of case-control studies suggested a potential association between MMP-3 polymorphisms, including rs3025058, and ischemic stroke, another meta-analysis found no such link." (PMID 40724896, 2025). "Thus, future studies need to investigate the role of MMP-3 in neuron survival post ischemic stroke." (PMID 39273389, 2024). "MMP-3 gene polymorphisms were associated with ischemic stroke but not ICH in the Korean population." (PMID 23565108, 2013). "No previous reports have clearly compared the time-dependent expression of different MMPs (MMP-9, MMP-3, MMP-2) after r-tPA treatment in ischemic stroke and their presence in neuronal or vascular compartments." (PMID 39273389, 2024). "Our findings indicate that in experimental ischemic stroke with reperfusion, the duration of ischemia and r-tPA treatment significantly impacts the expression of MMP-2, MMP-3, and MMP-9, as well as the extent of ischemic brain injury and neurological outcomes." (PMID 39273389, 2024). "The 21 ischemic stroke genes overlapping with genes that code for ECM-related proteins included COL3A, MMP1, MMP12 and MMP3." (PMID 33730931, 2021). "We demonstrated TGF-019 has sufficient sensitivity for the specific MMPs suspected in evoking HT during ischemic stroke, i.e., MMP2, MMP9, and MMP3." (PMID 30723388, 2019). "Following an ischemic stroke, breakdown of the BBB, vasogenic edema, and hemorrhagic conversion are mainly mediated by MMPs, in particular MMP-3 and MMP-9, which have been shown to be critical in inflammation-mediated neurovascular damage." (PMID 29527151, 2018). "MMP2, MMP3 and MMP9 are critical MMPs involved in BBB opening after ischemic stroke." (PMID 37611902, 2024). "Additionally, activated matrix metalloproteinases (MMPs), such as MMP-2, MMP-3, MMP-7, and MMP-9, induce BBB disruption in experimental ischemic stroke and severe inflammatory response following septic shock." (PMID 31547411, 2019). "MMP-2, MMP-3 and cathepsin L showed a smaller AUC and had no predictive effects on ischemic stroke." (PMID 32982940, 2020).
colon cancer (24 papers, 2012 to 2026). "In our previous study, C. militaris grown on germinated soybeans suppressed mRNA expression levels of MMP-9 and MMP-3 in colon cancer tissues." (PMID 39940873, 2025). "Cellular experiments confirmed aspirin downregulated metastasis‐related genes (E2F1, CCNE1, VEGFA, MMP3) in colon cancer." (PMID 41425852, 2025). "A total of 27 anticolon cancer targets of THCQF were selected, among which four genes (CCNB1, CCNA2, IL1A, and MMP3) were shown to effectively predict patient outcomes in a prognostic colon cancer model." (PMID 35479514, 2022). "ChIP-qPCR analysis showed that the DNA-binding affinity of STAT3 was significantly reduced at the known target genes such as Snail, Spg20, Mmp3 in the colon cancer cells with STAT3del, especially in the SW480 cells with STAT3del." (PMID 33535185, 2021). "In 2004, Denys examined over 12 factors activating or inhibiting tumor invasiveness in colon cancer cell lines and found a striking MMP3 overexpression in tumor cell lines compared to normal fibroblast lines obtained from the same patients." (PMID 29304854, 2018). "This is a direct effect since 5-HT induces MMP-3 mRNA levels in human colon cancer Caco-2 cells and MMP-9 mRNA in human primary culture of leucocytes." (PMID 27478308, 2016). "We have previously found that integrinβ6 was able to induce the migration and invasion of colon cancer cells by up-regulation of MMP-3/MMP-9." (PMID 27835891, 2016). "Additionally, AC treatment also inhibited the expression of NF-κb and C-myc; and MMP3 across all three-colon cancer cell lines." (PMID 31349708, 2019). "To predict whether miRNAs target Mmp3, Mmp10, and/or Mmp13 in murine colon cancer cells, we first utilized the bioinformatics algorithms TargetScan, miRWalk, microRNA.org, and RNA22." (PMID 25742789, 2015). "Furthermore, AC also down-regulates the EMT-related gene such as vimentin and MMP3 with the upregulation of miRNA expression of miR142-3p across all the three colon cancer cells, implicating the key regulatory function of miR142-3p in colon cancer stemness and metastasis." (PMID 31349708, 2019). "It is also observed that senescent colon cancer cells can promote EMT in adjacent cells through IL-6, MMP-3, FGF, and HGF, potentially facilitating tumor metastasis." (PMID 41614944, 2026). "Before we started, we detected the expression levels of MMP3, MMP9, TIMP1, VEGFA in various colon cancer cell lines by qRT-PCR assay, and found that these genes were highly expressed in RKO and SW480, and we chose RKO and SW480 for the following experiments." (PMID 39177661, 2024). "Together, these results demonstrate the significance of CCL3, MMP3, and TIMP1 in recruiting and regulating infiltrating immune cells in colon cancer." (PMID 36742294, 2023). "The results revealed that CCL3, MMP3, and TIMP1 expression was positively correlated with the infiltration status of immune cells like DCs, CD8+ T cells, and neutrophils in colon cancer." (PMID 36742294, 2023). "When colon cancer cells were treated with 20, 40 and 60 μmol/L NCTD for 24 h, the activity of MMP-3 and MMP-9 decreased substantially in a dose-dependent manner." (PMID 26846153, 2016). "Β6-siRNA encapsulated in TLPs was more likely to inhibit the activation of MMP-3 and MMP-9 than Lipo2000 and NTLPs (P < 0.01), which possibly resulted in the higher suppression of migration and invasion of colon cancer cells." (PMID 27835891, 2016). "The inhibitory effects of EVO on JAK2/STAT3 signaling and MMP3 expression were stronger than those of AG490, suggesting that EVO is a strong inhibitor of tumor cell migration in colon cancer." (PMID 26580615, 2015). "The effect of IL-1β and IP6 on the expression of mRNA of MMP-1, MMP-2, MMP-3, MMP-9, MMP-10, and MMP-13 and that of their tissue inhibitors TIMP-1 and TIMP-2 in colon cancer cells using real-time QRT-PCR assay was determined." (PMID 22415590, 2012).
colon cancer (continued). "In addition, CCL3, MMP3, and TIMP1 expression were negatively correlated with tumor purity in colon cancer (P = 2.30e-8, cor = -0.273; P = 6.68e-5, cor = -0.196 and P = 7.41e-16, cor = -0.385, respectively)." (PMID 36742294, 2023). "The reduction of MMP-1 and MMP-3 expression was reported to correlate with the inflammatory cytokine IL-6, signal transducer and activator of transcription (STAT), and the AP-1 (IL-6/STAT-1/AP-1) axis in colon cancer." (PMID 36839884, 2023). "In addition, results show a significant positive correlation between CCL3, MMP3, and TIMP1 expression and different immune cell types including dendritic cells, macrophages, CD8+ T cells, and neutrophils in patients with colon cancer." (PMID 36742294, 2023). "Therefore, we next analyzed if there was a correlation between the expression of hub genes such as CCL3, MMP3, and TIMP1 and infiltrating immune cells in colon cancer." (PMID 36742294, 2023). "Hence, we used the TIMER database to analyze the correlation between CCL3, MMP3, and TIMP1 expression and immune cell infiltration status in patients with colon cancer." (PMID 36742294, 2023). "Importantly, aspirin also inhibited the expression of four highly expressed metastatic genes in colon cancer, including E2F1, CCNE1, VEGFA, and MMP3, which may explain its anti‐tumor and anti‐metastasis effect." (PMID 41425852, 2025). "In addition, we confirmed at the cellular level that aspirin has the ability to inhibit the metastasis of colon cancer cells and demonstrated that aspirin can suppress the expression of metastasis‐related genes (E2F1, VEGFA, MMP3, and CCNE1) in colon cancer cells." (PMID 41425852, 2025). "In this study we have used comparative gene expression analysis and promoter mapping to demonstrate a direct link between IL-6 and MMP expression in colon cancer, via STAT-1 and novel non-canonical SBEs identified in the MMP-1 and MMP-3 proximal promoters." (PMID 28819304, 2017).
glioma (24 papers, 2013 to 2025). A benign or malignant brain and spinal cord tumor that arises from glial cells (astrocytes, oligodendrocytes, ependymal cells). "GFAP, NEFL, FABP4 and MMP3 are useful for differential diagnosis and prognosis, and are associated with molecular changes in gliomas." (PMID 38879494, 2024). "We speculate such losses, especially within the context of high MMP3 activity, may encode molecular events underlying movement in C6 glioma cells." (PMID 30941001, 2019). "Increased expression of MMP-3/9 has been associated with glioma progression." (PMID 28969029, 2017). "This activation would then lead to subsequent activation of downstream effectors that participate in the migration and invasiveness of glioma cells, in particular, matrix metalloproteinase‐3 (MMP‐3)." (PMID 39791545, 2025). "A biostatistical analysis of data from 276 histologically confirmed gliomas found that a high level of MMP3 expression and a low level of MMP10 were directly related to worse survival." (PMID 38474106, 2024). "Given the important roles of MMP3 in the progression of glioma cells, we sought to functionally validate the role of MMP3 in mediating GMPPB-induced GBM proliferation and invasion and its relationship with the Hippo pathway." (PMID 37834154, 2023). "For instance, elevated expression of MMP3 has been detected in human astrocytoma, especially in invasive glioma cells." (PMID 33608513, 2021). "Increased cytoplasmic MMP3 expression stimulates glioma cell invasiveness and migration, making MMP3 a promising therapeutic target." (PMID 33608513, 2021). "Demonstrating the selective engagement of ECM remodelling networks, data presented here confirm the binary increase, activity and inhibition of MMP3 using the condition media of glioma cells." (PMID 32156166, 2020). "We have found C6-13 demonstrates behaviors typical of aggressive glioma – increased migration, changes in the actin cytoskeleton, increased expression of osteopontin and MMP3, and ECM remodeling via increased of MMP activity." (PMID 30941001, 2019). "The upregulated CLC-3 in gliomas promotes NF-κB transactivity to regulate intracellular transcriptomic plasticity, alters matrix metalloproteinase such as MMP-3, MMP-9 expression, and actively modulates the extracellular environment." (PMID 28969029, 2017). "While the basis for this remains to be elucidated, available evidence suggests that MMP3 is a direct target for miR-15b in glioma cells." (PMID 27070581, 2016). "Our group has previously reported that specific inhibitors of MMP-3 or -9 significantly inhibited the invasion in PMA-induced U87MG glioma cells." (PMID 27043542, 2016). "Also, in a study on glioma cells, the upregulation of the Bmi-1 gene promoted cell migration and invasion via the NF-kB-mediated upregulation of MMP-3." (PMID 38137108, 2023). "Our study shows that high motility gliomas expressing Cx43 differ from their parental counterparts by the upregulation of MMP3, osteopontin, aldo-keto reductase family 1 member B10 (ARK1B10), and to a lesser degree SERPINE2 (2.5-fold, P = 0.03), and phosphoglycerate kinase 1 (2.4-fold, P = 0.04)." (PMID 30941001, 2019). "In addition, MMP-3 plays a critical role in glioma invasiveness through degradation of hyaluronic acid-rich matrix of the brain." (PMID 27043542, 2016). "Subsequently, we further analyzed the previous transcriptome sequencing data and found that silencing PRMT6 in glioma cells can reduce the expression of invasion-related molecules (TGFB1/2, MMP3/9/14, FN1, ROCK2, etc.)." (PMID 39043634, 2024). "We identified 8 plasma proteins which were increased in gliomas vs. meningiomas (GFAP, NEFL, EDDM3B, PROK1, MMP3, CTRL, GP2, SPINT3) and 4 proteins which were decreased in gliomas vs. meningiomas (FABP4, ALDH3A1, IL-12B and OXT)." (PMID 36959545, 2023). "As our results attribute peritumoral PNN degradation primarily to glioma-released MMPs (MMP-2, MMP-3, and MMP-9), we used a cocktail of these MMPs to degrade PNNs experimentally." (PMID 30413686, 2018).
glioma (continued). "Knockdown of CLC-3 with ShCLC-3 adenovirus inhibits transcriptional activity of NF-κB, reduces MMP-3 and MMP-9 expression and decreases glioma cell migration and invasion." (PMID 28969029, 2017). "Consistent with the PCR results, an ELISA assay of MMP-3 further demonstrated that knockdown of CLC-3 significantly decreased MMP-3 protein expression in U87MG and SNB19 glioma cells." (PMID 28969029, 2017). "For instance, SAA is able to induce the production of MMP-2 and MMP-3 in synovial fibroblasts, MMP-9 activity in monocytic cells and MMP-2 and 9 activity in glioma cell lines." (PMID 24614130, 2014). "Glycitein down-regulates the expression of MMP3 and MMP9 to inhibit glioma cell invasion." (PMID 39338323, 2024). "According to Western blotting results, TUSC7 overexpression group had significantly lower expressions of MMP2, MMP3 and MMP9 than NC group, whereas they were obviously elevated after silencing TUSC7, suggesting that TUSC7 could inhibit the migration of glioma cells by degrading MMP2, MMP3 and MMP9." (PMID 37100464, 2023).
Obesity (24 papers, 2012 to 2025). Accumulation of substantial excess body fat. "Few human studies have been conducted on the metabolic role of Mmp3, yet a polymorphism in the MMP3 gene (Lys45Glu or G allele carriers) was associated with a higher risk of severe obesity compared with A/A genotype carriers in a Tunisian population." (PMID 37445827, 2023). "Previous studies, but not all, that have examined the association between MMP‐3 and obesity have found MMP‐3 to be upregulated in mice with nutritionally induced and genetic obesity (i.e., ob/ob and db/db mice)." (PMID 34110720, 2021). "Individuals carrying the MMP-3 45G or MMP-12 -82G variants were also associated with a higher risk for severe forms of obesity (MMP-3: OR = 1.9, P = 0.002; MMP-12: OR = 2.63, P = 0.003)." (PMID 29317790, 2017). "Macrophages are an important contributor to obesity‐associated inflammation, and the cross‐talk between macrophages and adipocytes/preadipocytes may play a key role in the progression of obesity‐associated central arterial stiffness, particularly in the context of MMP‐3‐associated ECM remodeling." (PMID 34110720, 2021). "Among them, MIP‐1γ, MMP‐3, VEGFR2, IGF‐1, and HGFR are associated with obesity and OPN and OPG are associated with atherosclerotic diseases." (PMID 39001701, 2024). "The present study demonstrated that a single bout of moderate- or high-intensity intermittent exercise in individuals with overweight or obesity resulted in an acute and transient increase in MMP-3 and decrease in OPN." (PMID 36648516, 2023). "MMP3 appears to contribute to the multiple molecular aspects of insulin resistance pathogenesis in obesity through inflammation since treatment with an MMP3 inhibitor abolished MMP3-mediated secretion of TNFα." (PMID 37445827, 2023). "For example, attenuation of MMP-3 in female mice with high-fat diet-induced obesity was followed by increased fat cells." (PMID 37372128, 2023). "Respondents are also patients who routinely seek treatment at the hospital orthopedic clinic and have received anti-inflammatory drugs so that the impact of obesity on MMP3 expression has been reduced." (PMID 37000824, 2023). "Knocking out the MMP3 gene results in adipocyte hypertrophy in mice when exposed to a high fat diet, as well as hyperphagia and obesity." (PMID 36575541, 2022). "Both excessive compressive mechanical force and high fat diet induced obesity caused TMJ osteoarthritis-like changes and increased expression of IL-1β, MMP-3, and leptin." (PMID 33060739, 2020). "In the current report, when individuals were stratified by BMI, the MMP-3 45Glu (G) and MMP7 (-181G) variants were more frequent in individuals with severe forms of obesity." (PMID 29317790, 2017). "The impact of MMP-1 (-519A/G, -1607 1G/2G), MMP-3 Lys45Glu (A/G), MMP-7 -181A/G, and MMP-12 -82A/G variants and plasma MMP levels on obesity and microvascular reactivity in Tunisians." (PMID 29317790, 2017). "MMP-3 Lys45Glu (A/G), MMP-7 (-181A/G), and MMP-12 (-82A/G) variants were associated with obesity and its anthropometric indicators." (PMID 29317790, 2017). "Adipogenesis and insulin sensitivity in obesity are also reported to be regulated by retinoid-related orphan receptor γ (RORγ) through its target gene MMP3 (matrix metalloproteinase-3 gene), which controls adipocyte size and insulin resistance in obesity." (PMID 28231175, 2016). "Altogether, these observations converge to the notion that TIMP4 is an important factor for adipose tissue differentiation and lipid absorption in response to nutrient excess and governs, with MMP3, depot- and sex-dependent adipose tissue expansion during obesity." (PMID 37445827, 2023). "However, upon a HFD, GWAT expresses higher levels of MMP3 as compared to ScWAT suggesting a depot-specific regulatory role of MMP3 in obesity." (PMID 37445827, 2023). "This upregulation in MMP‐3 may be partly attributable to the milieu of inflammatory factors secreted by macrophages in obesity." (PMID 34110720, 2021).